RNU4-20P (RNA, U4 small nuclear 20, pseudogene)
Gene: Small nuclear RNA gene on chromosome 12 (59,586,793 to 59,586,943, reverse strand). Ensembl gene ENSG00000202471.
Homologues: Orthologues: chimpanzee U4 (90% identical), tropical clawed frog U4 (66% identical), guinea pig U4 (56% identical), rat LOC120093503 (52% identical), mouse Gm22717 (51% identical), rabbit U4 (48% identical), dog U4 (46% identical). Paralogues in human: RNU4-67P (77% identical), RNU4-76P (74% identical), RNU4-13P (73% identical), RNU4-7P (73% identical), RNU4-68P (72% identical), RNU4-42P (71% identical), RNU4-58P (71% identical), RNU4-80P (71% identical), RNU4-45P (70% identical), RNU4-16P (70% identical), RNU4-44P (70% identical), RNU4-23P (69% identical), and 81 more.